CXCL17 (C-X-C motif chemokine ligand 17)
Diseases named in the same sentence as CXCL17 in open-access papers (continued):
Sharing a sentence is not in itself a finding about the gene and the disease.
cancer (continued). "In this study, we provide data that reveals the novel functions of CXCL17 on the establishment of supportive lung metastatic niches for cancer by recruiting CD11b+Gr-1+ MDSCs, which in turn support angiogenesis, cancer extravasation, and survival in new microenvironments." (PMID 30755260, 2019). "In contrast to CEACAM5 and CXCL17, two markers demonstrated lower levels in the plasma of cancer patients: VEGFR2 acts as a cell-surface receptor for vascular endothelial growth factors (VEGFA, VEGFC and VEGFD), and is involved in angiogenesis in both physiological and pathological conditions." (PMID 31357969, 2019). "It is possible that some of these, such as the orphan chemokine CXCL17, recently shown to promote angiogenesis and cancer progression, could also be involved in regulating metastatic dissemination via the IL-13 pathway." (PMID 26208975, 2015). "Given that soluble factor CXCL17 is mainly responsible for recruiting immune cells in the lung, a critical step for the formation of metastatic niche favored by the cancer, so we speculated that CXCL17 might function through remodeling of the lung microenvironment in a paracrine manner." (PMID 30755260, 2019). "Therefore, it is possible that CXCL17 expression may be acquired in the late process of cancer progression (or development)." (PMID 22952881, 2012). "There are a few chemokines that are positively correlated with ASPP1 in cancers, such as CCL28, CX3CL1, CXCL14, and CXCL17." (PMID 39830645, 2024). "Specifically, CXCL17 and CXCL5 were increased in cancers with high proliferation as assessed by Ki67 and decreased in cancers with high ER levels." (PMID 30451357, 2019). "The analysis demonstrated that expression of four of six proteins (CCL13, IL‐6, CXCL17, and DCN) also differed between the benign lesions and cancer." (PMID 30451357, 2019). "While a consistent negative correlation with a single gene across most cancers was rare, it was a defining feature for a few chemokines, most notably CXCL17 and CCL28." (PMID 41614761, 2025). "Moreover, for CTSE, CXCL17, and LYZ, we explored the correlation between their expression and CLDN18.2 expression in three cancers." (PMID 39555091, 2024). "CXCL17 and CX3CL1 were positively correlated with SUSD4 expression level in most types of cancer." (PMID 38579174, 2024). "We also elucidated the clinical significance of CXCL17 and GPR35, explored the potential pathways by which they participate in GC development thorough TCGA analysis, and analyzed their involvements in drug sensitivity by the Cancer Therapeutics Response Portal (CTRP) database." (PMID 36614059, 2022). "Although CXCL17-positive cancer cell lines had aggressive phenotypes in xenogeneic transplantation studies using SCID mice, even overexpression of CXCL17 in less metastatic cell lines without CXCL17 expression led to metastatic growth in the liver." (PMID 22952881, 2012).
infection (14 papers, 2012 to 2026). The state of being infected such as from the introduction of a foreign agent such as serum, vaccine, antigenic substance or organism. "CXCL17, the most recently identified member of the chemokine family, has been implicated in angiogenesis, tumorigenesis, infection, and inflammation across various tumors." (PMID 42255223, 2026). "CXCL17-deficient mice have also been reported to be less resistant to infection in a mouse model of herpes simplex virus infection, although this was postulated to be a result of impaired trafficking of GPR35+ cytotoxic T cells." (PMID 37942327, 2023). "Respiratory parameters, airway inflammation, and airway injury were assessed in CXCL17-overexpressing mice through adeno-associated virus vector Type 5 (AAV5) infection." (PMID 37624152, 2023). "Analysis of CXCL17 expression in lung biopsy specimens obtained early during the infection would have clarified this point." (PMID 33717172, 2021). "Our results show that CXCL17 production increases in the lung of M. tuberculosis–infected mice during acute and chronic stages of infection." (PMID 34561226, 2021). "In this study, we evaluated the function of CXCL17 in a mouse model of aerosol infection with the clinical W-Beijing lineage Mycobacterium tuberculosis hypervirulent HN878 strain." (PMID 34561226, 2021). "Our results indicate that murine M. tuberculosis HN878 infection induces CXCL17 production within the lung and in both epithelial and myeloid cells after early and late time points following infection." (PMID 34561226, 2021). "Up-regulated gene expression of four AMPs (Chi3l1, Cxcl17, Lcn2, Spli) was found in the lungs during the whole course of infection." (PMID 25137043, 2014). "For example, the gene expression levels of the cytokines Cxcl1, Cxcl2, Cxcl5 and Cxcl17 was in agreement with the recruitment of neutrophils and DCs towards the site of infection." (PMID 25137043, 2014). "Additionally, these cells produce chemokines, such as CCL9 and CXCL17, that are responsible for attracting innate immune cells to the site of infection or inflammation." (PMID 37408269, 2023). "Such a process may permit the retention and oligomerization of CXCL17 on mucosal surfaces to create high local concentrations at pathogen infection routes." (PMID 37942327, 2023). "Despite this, we speculate that lung and serum CXCL17 levels may increase as the infection with SARS-CoV-2 progresses in patients with severe disease." (PMID 33717172, 2021). "Moreover, we demonstrate that both macrophages and lung epithelial cells can become sources of CXCL17 after infection with the influenza A(H1N1) pdm09 virus." (PMID 33717172, 2021). "However, CXCL17 expression is dispensable following hypervirulent M. tuberculosis HN878 infection in mice." (PMID 34561226, 2021). "Consistent with such a function, CXCL17 expression by epithelial cells has been reported to be induced following challenge of mice with Mycobacteria, although CXCL17-deficient mice were found to be no more susceptible to infection than wild-type littermates." (PMID 37942327, 2023). "Furthermore, CXCL17 treatment attracts monocytes to the site of M. tuberculosis HN878 infection." (PMID 34561226, 2021). "However, CXCL17−/− mice are not more susceptible to M. tuberculosis HN878 infection than wild-type (WT) controls." (PMID 34561226, 2021). "Our study is the first to report on difference in TLR5, CXCL17, CCL26, IL1RL2, or IL3RA levels in sexes during infection." (PMID 36171541, 2022). "In contrast, the infection with icSARS ExoNI and icSARS dNSP16, which are attenuated mutant strains of SARS-CoV, upregulated the expression of CXCL17." (PMID 33717172, 2021).
cardiovascular diseases (1 paper, 2019). "A recent study exhibits that GPCR35 acted as the receptor of CXCL17 and is closely related to cardiovascular disease." (PMID 31934638, 2019). "Recent studies have found that GPR35, the receptor for chemokine (C-X-C motif) ligand 17 (CXCL17), is closely related to cardiovascular diseases." (PMID 31934638, 2019).
heart disease (1 paper, 2025). "Proteins such as CDCP1, CXCL17, FGF21, GDF15, and IGFBP4 commonly mediated effects in both the Air and Noise Pollution and Social Deprivation groups, while GDF15 was notably linked to heart disease across these patterns." (PMID 41290610, 2025).
infectious disease (1 paper, 2021). A disorder directly resulting from the presence and activity of a microbial, viral, or parasitic agent in humans. "This, along with data from our current study indicates that CXCL17 is very likely to have important functions in the pathogenesis of inflammatory/infectious diseases of the lung as well." (PMID 33717172, 2021).
respiratory diseases (1 paper, 2025). "For example, higher levels of CXCL17, a protein involved in homeostasis at mucosal barriers and inflammatory response in respiratory diseases, were associated with older age, smoking, and amount of exhaled CO in our study." (PMID 41071435, 2025).
CXCL17 also shares sentences with these, for which no sentence is quoted: Hepatic fibrosis (2 papers); acute myocardial infarction (1); bacterial infection (1); bladder cancer (1); colon mucinous adenocarcinoma (1); connective tissue disease (1); gastric tumors (1); Hypertension (1); liver cancer (1); liver cirrhosis (1); melanoma (1); non-small cell lung carcinoma (1); pancreatic ductal adenocarcinoma (1); rectal mucinous adenocarcinoma (1); rectosigmoid adenocarcinoma (1); renal failure (1); squamous cell carcinoma (1); systemic sclerosis (1); thyroid carcinoma (1); triple-negative breast carcinoma (1); unstable angina (1); unstable angina pectoris (1); Wilms tumor (1).